ETV2 (ETS variant transcription factor 2)
Description:
Binds to DNA sequences containing the consensus pentanucleotide 5'-CGGA[AT]-3'.
Synonyms: ER71; ETSRP71
Tractability: PROTAC: ubiquitination databases record sites on it.
Gene: Protein-coding gene on chromosome 19 (35,641,745 to 35,644,871, forward strand). Ensembl gene ENSG00000105672.
Subcellular location: Nucleus
Gene Ontology:
Molecular function: sequence-specific double-stranded DNA binding; DNA-binding transcription factor activity, RNA polymerase II-specific; DNA-binding transcription activator activity, RNA polymerase II-specific; DNA-binding transcription factor activity; RNA polymerase II cis-regulatory region sequence-specific DNA binding; sequence-specific DNA binding
Biological process: cell differentiation; regulation of transcription by RNA polymerase II; positive regulation of transcription by RNA polymerase II; regulation of DNA-templated transcription
Cellular component: nucleus
Genetic constraint (gnomAD): Loss-of-function variants: 27 observed, 25.71 expected, observed/expected ratio (o/e) 1.05, 90% interval 0.77 to 1.45. The upper end of that interval is the gene's LOEUF score, 1.45, which puts it in group 5 of 6, group 1 being the genes least tolerant of losing a copy. Missense variants: 507 observed, 430.8 expected, observed/expected ratio (o/e) 1.18, 90% interval 1.09 to 1.27. Synonymous variants: 207 observed, 184.49 expected, observed/expected ratio (o/e) 1.12, 90% interval 1 to 1.26.
Homologues: Orthologues: chimpanzee ETV2 (98% identical), macaque ETV2 (91% identical), dog ETV2 (73% identical), pig ETV2 (69% identical), mouse Etv2 (67% identical), rat Etv2 (66% identical), guinea pig Etv2 (36% identical). Paralogues in human: ETS1 (28% identical), ETS2 (28% identical), FLI1 (26% identical), ERG (23% identical), GABPA (22% identical), ETV4 (20% identical), ETV5 (20% identical), ETV1 (19% identical), FEV (18% identical), ETV6 (16% identical), ELF2 (16% identical), ERFL (16% identical), and 16 more.
Diseases named in the same sentence as ETV2 in open-access papers:
ETV2 is named in the same sentence as 31 diseases in open-access papers, as found by Europe PMC text mining. Sharing a sentence is not in itself a finding about the gene and the disease. The quoted sentences say what the papers report.
atherosclerosis (3 papers, 2019 to 2024). A disease characterized by the build-up of fatty material and calcium deposition in the arterial wall resulting in partial or complete occlusion of the arterial lumen. "The marker genes for these clusters were then analyzed using KEGG Enrichment, and Etv2#2 and Sox17-Erg#2 were selected for further investigation based on the enrichment for focal adhesion and fluid shear stress and atherosclerosis." (PMID 38755186, 2024). "Preclinical testing of ETV2 in inflammatory vascular diseases (e.g., atherosclerosis) would also be important since vascular diseases are often accompanied with chronic inflammation." (PMID 31534512, 2019). "Because vascular injury plays a crucial role as an initial trigger in the development of different vascular disorders, such as atherosclerosis, ETV2 may serve as an important factor linking endothelial cells and smooth muscle cells in response to vascular injury." (PMID 37373052, 2023).
glioblastoma (3 papers, 2018 to 2023). The most malignant astrocytic tumor (WHO grade IV). "The role of Etv2 in pathological angiogenesis was also demonstrated in glioblastoma multiforme (GBM), a malignant tumor with high recurrence." (PMID 36927793, 2023). "Further, ETV2 can stimulate the reprogramming of glioblastoma neural stem-like cells into cells with an endothelial phenotype." (PMID 31534512, 2019). "Stimulating Etv2 gene expression in glioblastoma neural stem cells prevented the activation of genes involved in neural differentiation and activated genes required for vascular development." (PMID 29527330, 2018). "Additionally, deletion of ETV2 in glioblastoma inhibits this process, suggesting novel functions of ETV2 in tumor-derived endothelial cell generation (i.e., vasculogenesis)." (PMID 31534512, 2019). "As an initial step to test this hypothesis, we first investigated the expression of ETV2 in clinical brain tumor specimens, including glioblastoma (GBM grade III–IV, n = 81), astrocytoma (grade I–II, n = 86), meningioma (grade I–II, n = 48), and oligodendroglioma (grade I–II, n = 7)." (PMID 29527330, 2018).
myocardial infarction (3 papers, 2019 to 2023). Gross necrosis of the myocardium, as a result of interruption of the blood supply to the area, as in coronary thrombosis. "Importantly, intramyocardial injection of the adeno-associated virus form of ETV2 into rat hearts with induced myocardial infarction designed for clinical applicability consistently resulted in significant augmentation of cardiac function." (PMID 30755583, 2019). "ETV2 has been reported as a potential therapeutic target for myocardial infarction and a key regulator of vascular regeneration in hind limb animal models through endothelial remodeling." (PMID 37373052, 2023). "We provide compelling evidence that ETV2 has a robust effect on vascular regeneration and enhanced cardiac repair after myocardial infarction, highlighting a potential therapeutic function of ETV2 as an efficient means to treat failing hearts." (PMID 30755583, 2019). "In addition, ETV2 has been reported as a potential therapeutic target for myocardial infarction and a key regulator of vascular regeneration in hind limb animal models through endothelial remodeling." (PMID 37373052, 2023). "In addition, the transduction of ETV2 improves cardiac function and induces vascular regeneration in animal models of myocardial infarction." (PMID 37373052, 2023). "Thus, the objective of this study was to explore the therapeutic potential of ETV2 in murine models of myocardial infarction in vivo." (PMID 30755583, 2019).
glioma (2 papers, 2018 to 2021). A benign or malignant brain and spinal cord tumor that arises from glial cells (astrocytes, oligodendrocytes, ependymal cells). "More importantly, we performed some in vitro experiments to confirm the function of ETV2 in glioma cells." (PMID 33732284, 2021). "ETV2 was highly expressed in high-grade glioma (grade III–IV GBM)." (PMID 29527330, 2018). "We noticed that the ETV2 expression level varied even in high-grade glioma." (PMID 29527330, 2018). "Together, these data indicate that ETV2 is significantly enriched in high-grade glioma." (PMID 29527330, 2018). "More importantly, in vitro experiment revealed that ETV2 is involved in the migration, invasion, and EMT process of glioma cells." (PMID 33732284, 2021). "The results showed that ETV2 can contribute to the invasion, migration, and epithelial-mesenchymal transition (EMT) process of glioma." (PMID 33732284, 2021). "Therefore, we investigated whether ETV2 mediates EMT in glioma." (PMID 33732284, 2021). "The results showed that ETV2 was more highly expressed in glioma and contributed to the invasion, migration, and epithelial-mesenchymal transition (EMT) process of glioma." (PMID 33732284, 2021). "We also tested the expression of ETV2 in the SHG44 and A172 cell lines with q-PCR, and the expression of ETV2 in glioma cell lines (SHG44 and A172) was higher than that in the normal human cell line (HEB)." (PMID 33732284, 2021).
acute myeloid leukemia (1 paper, 2026). Acute myeloid leukemia (AML) is a group of neoplasms arising from precursor cells committed to the myeloid cell-line differentiation. "Erythroid acute myeloid leukemia (AML) cell line OCI-M2 expresses a particular oncogenic network: IRF6, in concert with ETV2 and HEY1, aberrantly activates NKL homeobox gene NKX2-4, which in turn represses megakaryocytic lineage factor FLI1." (PMID 41892358, 2026).
alopecia (1 paper, 2022). Hair loss usually from the scalp. "Some members of this family, such as ETV2, have been found to promote hair growth through vascular regeneration in chemotherapy-induced alopecia, while Elf5, another ET family member, is expressed in the inner root sheath of hair follicles." (PMID 35625530, 2022).
anemia (1 paper, 2022). A reduction in the number of red blood cells, the amount of hemoglobin, and/or the volume of packed red blood cells. "Interestingly, a compound heterozygous combination with ~20% of normal Etv2 expression resulted in embryonic lethality at E10.5 with severe anemia but with apparently normal vascular development." (PMID 35649376, 2022).
arteriovenous malformations (1 paper, 2018). "Furthermore, knock-down of FOXC2 in combination with Etv2 has been shown to disrupt vascular development in the zebrafish and mouse embryo compound mutants for FOXC1 and FOXC2 display arteriovenous malformations." (PMID 29963552, 2018).
astrocytoma (1 paper, 2018). "Among the 222 tumor samples, positive ETV2 expression was observed in 76.5% (62/81) of GBM and in 39.7% (56/141) of the low-grade brain tumor (astrocytoma, oligodendroglioma, and meningioma) but not in normal brain tissues (P < 0.0001)." (PMID 29527330, 2018).
brain tumor (1 paper, 2018). "The expression levels of ETV2 in different brain tumor and normal brain (n = 16) samples were analyzed by IHC (immunohistochemistry) and western blotting." (PMID 29527330, 2018). "Occasionally, ETV2 expression was detected in low-grade brain tumors." (PMID 29527330, 2018). "Intriguingly, we observed that some ETV2+ GBM tumor cells appeared to have vascular structures (dotted lines), while ETV2+ tumor cells in low-grade brain tumors were randomly distributed." (PMID 29527330, 2018).
Ewing sarcoma (1 paper, 2025). A small round cell tumor that lacks morphologic, immunohistochemical, and electron microscopic evidence of neuroectodermal differentiation. "In PLGC samples, the second and third most enriched motifs were Ets Variant Transcription Factor 2 (ETV2, P = 1 × 10-3093, 8.61%) and Ewing sarcoma (EWS, P = 1 × 10-2555, 8.01%)." (PMID 41551593, 2025).
fibrosis (1 paper, 2019). the formation of excess fibrous connective tissue in an organ or tissue in a reparative or reactive process. "Importantly, Masson’s trichrome staining of cardiac tissues harvested at 8 weeks also confirmed that the ETV2-injected group showed significantly reduced cardiac fibrosis compared to the control group (16.3 ± 2.4% in ETV2 vs. 39.1 ± 1.1% in control, n = 3; p < 0.05)." (PMID 30755583, 2019).
ischemic disease (1 paper, 2022). Lack of blood supply to an area of the body, resulting in impairment of tissue oxygenation. "Identifying this pioneer role for ETV2 has big implications for the development of regenerative therapies that aim to generate vasculature for ischemic diseases, particularly in the cardiovascular system." (PMID 36082116, 2022). "Future studies will need to focus on further characterization of the molecular mechanisms driving endothelial cell development/reprogramming by ETV2 to enhance therapeutic approaches to develop mature vasculature for ischemic diseases." (PMID 36082116, 2022).
melanoma (1 paper, 2025). A malignant, usually aggressive tumor composed of atypical, neoplastic melanocytes. "In melanoma, several ETS TFs, including FLI1, SPI1, ELF4, ETV7, SPIB, and SPIC, are expressed at higher levels in Cluster A patients, whereas ETV5, ETV4, ELK1, ERF, and ETV2 showed increased expression in Cluster B patients." (PMID 41502516, 2025).
myocardial ischemia (1 paper, 2023). A disorder of cardiac function caused by insufficient blood flow to the muscle tissue of the heart. "EC–VSMC interactions affect VSMC turnover and regulate the function of VSMCs; several reports have confirmed that ETV2 can induce the maturation of ECs, promote vascular development, and be used as a therapeutic agent in myocardial ischemia." (PMID 37373052, 2023).
neural tumor (1 paper, 2018). "To determine the origin of TDECs in primary patient GBM (p-GBM), we first co-stained for ETV2 with neural stem-like cell markers (Nestin, Vimentin, and CD133) or mature neural tumor cell makers (NeuN and GFAP) in cryosections of p-GBM autopsies." (PMID 29527330, 2018).
tumor (10 papers, 2012 to 2025). "Lung and sarcoma tumor xenografts were shown to be susceptible to siRNA polyplexes against factors that control tumor angiogenesis (ETV-2 and MYCT1) and the immunosuppressive tumor microenvironment." (PMID 37298407, 2023). "The activation of ETV2 in tumor-associated endothelial cells was shown to contribute to tumor angiogenesis." (PMID 35181635, 2022). "Importantly, Myct1 inhibition (i.e., Myct1 global knockout and Myct1 endothelial knockout) led to a reduction in tumor growth and angiogenesis, reminiscent of Etv2-deficient tumor vessel." (PMID 36927793, 2023). "For example, target genes of ETV2 and POGK, which are associated with cell differentiation and tumor angiogenesis, were specifically expressed in the uterus from the estrogen group." (PMID 39872660, 2024). "Recently, studies have demonstrated ETV2 mRNA expression and amplification in various tumor specimens, including glioblastoma and adrenocortical carcinoma." (PMID 35181635, 2022). "Along that line, it was recently shown in a zebrafish xenotransplantation model that Etv2 and Fli1b are required for tumor angiogenesis." (PMID 34153034, 2021). "More direct evidence on ROS-mediated Etv2 induction was shown in TAECs from lung carcinoma in a tumor graft mice model." (PMID 31534512, 2019). "The authors demonstrated that the deletion of Etv2 in endothelial cells or systemic delivery of siEtv2 into tumor bearing mice impairs tumorigenesis and angiogenesis." (PMID 31534512, 2019). "As discussed, reactivation of Etv2 occurs in TAECs, while interfering the function of ETV2 leads to decreased tumor angiogenesis in a mouse tumor model of xenotransplantation." (PMID 31534512, 2019). "Other investigations of various human malignant tumor tissues (lung, breast, prostate and colon) revealed that ETV2 is expressed in tumor-associated ECs (TAECs), but not in ECs from healthy controls." (PMID 36927793, 2023).
cancer (7 papers, 2019 to 2025). A tumor composed of atypical neoplastic, often pleomorphic cells that invade other tissues. "Furthermore, we discuss future directions to deploy the clinical potential of ETV2/ER71 as a novel and potent target for vascular disorders such as cardiovascular disease, neurovascular impairment and cancer." (PMID 36927793, 2023). "As ETV2 has been shown to have a role in cancer, understanding whether its ability to remodel silent/compacted chromatin as a pioneer factor has important implications during angiogenesis, as therapeutic initiatives could target and inhibit ETV2 thereby impacting tumorigenesis." (PMID 36082116, 2022). "Additionally, it would be interesting to determine whether or not BRG1 or another chromatin remodeler also forms a complex with ETV2 in the context of cancer." (PMID 36082116, 2022). "Considering the evolutionarily conserved function of ETV2 and the increasing importance of the lymphatic vessels in pathophysiological events including CVD and cancer 39-43, a further detailed investigation on the role of ETV2 in lymphatic compartment in mammals would be warranted." (PMID 31534512, 2019).
cardiovascular disease (4 papers, 2019 to 2023). "Altogether, these results strongly suggest that ETV2 alone and often together with other signaling molecules can directly convert non-ECs into functional ECs, which could have therapeutic potential for treating cardiovascular disease." (PMID 36927793, 2023). "In addition, recent reports on the novel functions of ETV2/ER71 in neovascularization and direct cell reprogramming are discussed with a focus on its therapeutic potential for cardiovascular diseases." (PMID 31534512, 2019).
infection (2 papers, 2015 to 2019). The state of being infected such as from the introduction of a foreign agent such as serum, vaccine, antigenic substance or organism. "Infection of adult human fibroblast and mesenchymal cells with an ETV2 virus in combination with FLI1 and ERG1 viruses only modestly induced endothelial genes." (PMID 25780560, 2015). "In our method of infection during mesoderm-directed differentiation, 60% of the ETV2 expressing cells were able to respond." (PMID 25780560, 2015). "This did not result in an absolute increase in endothelial-like cells as the slight increase in VE-CADHERIN-positive cells infected with ETV2-mCherry virus was counteracted by the decreased infection efficiency of these cells." (PMID 25780560, 2015). "The absolute number of cells that expressed VE-CADHERIN was significantly higher following ETV2-mCherry infection, increasing from an average of 645/10,000 cells in control conditions to 4,141/10,000 cells in ETV2 overexpression conditions." (PMID 25780560, 2015). "Based upon this knowledge, we anticipated that infection of differentiating hESCs with an ETV2-expressing virus at time points later than the peak of endogenous expression would result in decreasing percentages of cells responding to the exogenous signal." (PMID 25780560, 2015).
ETV2 also shares sentences with these, for which no sentence is quoted: vascular disorder (2 papers); brain ischemia (1); breast carcinoma (1); diabetes (1); endometrial cancer (1); heart failure (1); meningioma (1); oligodendroglioma (1); prostate carcinoma (1); stem cell leukaemia (1); viral infection (1).